SRPX (sushi repeat containing protein X-linked)
Diseases named in the same sentence as SRPX in open-access papers (continued):
Sharing a sentence is not in itself a finding about the gene and the disease.
cancer (15 papers, 2009 to 2025). A tumor composed of atypical neoplastic, often pleomorphic cells that invade other tissues. "SRPX has been identified through mRNA expression network analysis, and has been shown to suppress cancer cell stemness." (PMID 39010084, 2024). "ANLN, which plays a role in inhibiting cancer, and SRPX, which plays a role in promoting cancer, can be used as effective biomarkers to predict the prognosis and the efficacy of immunotherapy." (PMID 35548187, 2022). "SRPX2 expression was markedly up-regulated (20.5 fold, p = 0.00014) in cancer tissues, compared with paired noncancerous mucosa samples, whereas the putative tumor suppressor gene SRPX was down-regulated (0.7 fold, p = 0.029) in cancer." (PMID 22242148, 2012). "In general, SRPX2 was reported as overexpressed in cancer while SRPX and CCDC80 were identified as downregulated in malignant conditions." (PMID 20964819, 2010). "Previous research has established that SRPX expression is significantly downregulated in various cancers, including those of the lung, prostate, colon, and ovary, likely due to epigenetic modifications such as DNA methylation, or the activation of oncogenes like ras and src." (PMID 40463372, 2025). "Currently, SRPX is being examined as a potential cancer drug under patent number US 9,290,744 B2." (PMID 34681112, 2021). "Ectopic expression of the SRPX protein induced apoptosis in human cancer cell lines." (PMID 20964819, 2010). "In addition, SRPX has been reported to participate in the pathogenesis of cancers." (PMID 41312090, 2025). "However, whether SRPX can modulate immunity to control cancer progression and whether it can replace the depth of neutrophil infiltration remain unclear, and further research is needed." (PMID 34276767, 2021). "In many cancer-related microarray experiments (see Introduction section), P-DUDES genes showed diverse expression changes, although most often SRPX and CCD80 were downregulated whereas SRPX2 was upregulated." (PMID 20964819, 2010). "For other genes, such as SRPX and KIAA0372, more biomedical studies are needed to fully understand their roles in cancer." (PMID 19919702, 2009). "Interestingly, cancer exosomes, but not normal exosomes, modulated expression of matrix remodelling (EFEMP1, DDK3, SPARC), cell cycle (EEF2K), membrane remodelling (LAMP2, SRPX), differentiation (SPRR2E), apoptosis (CTSC), transcription/translation (KLF6, PUS7)." (PMID 30008265, 2018).
SRPX also shares sentences with these, for which no sentence is quoted: benign prostate hyperplasia (1 paper); brain disorder (1); clear cell carcinoma (1); colorectal tumour (1); endometrial cancer (1); epilepsy (1); glaucoma (1); Hernia (1); Inguinal hernia (1); language disorder (1); liver fibrosis (1); pilocytic astrocytoma (1); prostate adenocarcinoma (1); serous carcinoma (1); uterine corpus endometrial carcinoma (1).